DYRK1A (dual specificity tyrosine phosphorylation regulated kinase 1A)
Diseases named in the same sentence as DYRK1A in open-access papers (continued):
Sharing a sentence is not in itself a finding about the gene and the disease.
prostate carcinoma (5 papers, 2014 to 2023). A carcinoma that arises from epithelial cells of the prostate gland. "Prostate cancer is most likely to develop bone metastases, and prostate cancer-derived miR-378a-3p-containing EVs promote osteolysis by activating the Dyrk1a/Nfatc1/Angptl2 axis in bone marrow macrophages during tumor bone metastasis." (PMID 38037077, 2023). "MiR-378a-3p from prostate-cancer-cell-derived EVs promoted osteolysis through activation of the Dyrk1a/Nfatc1/Angptl2 axis in bone marrow macrophages, which played an important role in prostate cancer bone metastasis and could be a potential predictor of metastatic prostate cancer." (PMID 37046819, 2023). "Prostate-cancer-cell-derived EVs loaded with miR-378a-3p accelerated osteolysis by targeting the Dyrk1a/Nfatc1 axis to upregulate ANGPTL2 expression and secretion, thereby promoting PMN formation and enhancing prostate cancer metastasis." (PMID 37046819, 2023). "Although effective in other cases, notably against breast and prostate cancers, this avenue has not yet been exploited in the case of DYRK1A regulation Broad therapeutic implications related to DYRK1A’s roles as a tumor suppressor and mediator of radiosensitivity were highlighted in the past years." (PMID 36012629, 2022).
viral infection (5 papers, 2018 to 2025). "Hence, overexpression of DYRK1A could be at the root of the heterogeneous predisposition to viral infections and pathogenesis found in the T21 population." (PMID 40519271, 2025). "Despite the abundant reports demonstrating that DYRK1A plays many different functions during viral infections, a synthesis of such activities, and their implications in DS health and disease, is lacking." (PMID 40519271, 2025). "Here, the authors show that a protein kinase DYRK1A is required for protection from viral infection through the regulation of CSR and effective clonal expansion." (PMID 36927854, 2023). "Here, we find that the protein kinase DYRK1A is essential for B cell-mediated protection from viral infection and effective vaccination through regulation of class switch recombination (CSR)." (PMID 36927854, 2023). "In this work, we examine the function of DYRK1A during B-cell immune response to viral infection and to vaccine-derived antigens." (PMID 36927854, 2023). "We further reveal that DYRK1A performs its proviral role in the nucleus independently of kinase function, suggesting a previously undescribed mechanism of DYRK1A activity in viral infection." (PMID 37310920, 2023). "We find that DYRK1A is essential for protection from viral infection through CSR, mediated by phosphorylation of MSH6." (PMID 36927854, 2023). "We conclude that DYRK1A in B cells has an important function in mounting a protective immune response against viral infection." (PMID 36927854, 2023). "Based on these results, we conclude that after initial B-cell activation and CSR, DYRK1A restrains GC seeding during early stages of the response to vaccination or virus infection." (PMID 36927854, 2023). "Additional host factors that were significantly enriched include those described for other viral infections, such as negative-stranded RNA virus vesicular stomatitis virus (VSV) (ARFRP1, SYS1, and YKT6) and the human immunodeficiency virus (HIV) (SRP14, DYRK1A, and IL2RA) (33, –, 37)." (PMID 35502904, 2022).
amyloid (4 papers, 2019 to 2024). "Overproduction of Aβ may up-regulate DYRK1A expression and enhance the contribution of overexpressed DYRK1A to both neurofibrillary degeneration and associated neuronal loss and to the age-associated increase of amyloid load detected in this study." (PMID 34983655, 2022).
cardiomyopathy (4 papers, 2015 to 2024). A disease of the heart muscle or myocardium proper. "Our results reveal a significant role of DYRK1A in cardiac repair and suggest a drug target with translational potential for treating cardiomyopathy." (PMID 35810562, 2022). "In vitro and in vivo studies have demonstrated that overexpression of DYRK1A leads to increased phosphorylation of Ccnd2, promotes its subsequent proteasomal degradation and thus dysregulation, leading to compromised cardiomyocyte proliferation and finally cardiomyopathy." (PMID 36012629, 2022).
cervical cancer (4 papers, 2019 to 2025). A primary or metastatic malignant neoplasm involving the cervix. "Alterations to the DYRK1A expression might involve the miR-1246 known to target DYRK1A, which is significantly downregulated in lesions from cervical cancer patients in a manner associated with HPV infection." (PMID 32751160, 2020). "Earlier, increased expression of DYRK1A had been observed in keratinocytes immortalized with the oncogenic human papillomavirus HPV16 and in cervical cancer samples as compared to uninfected counterparts." (PMID 40519271, 2025).
depression (4 papers, 2021 to 2024). "Altogether, our findings suggest that miR‐211‐5p/Dyrk1A pathway dysregulation may represent an important risk factor associated with the neurobiological and behavioural responses involved in depression." (PMID 34121317, 2021). "However, whether Dyrk1A is involved in the pathogenesis of depression, in particularly its potential role during cell death and signalling pathways, is not clearly understood." (PMID 34121317, 2021). "Therefore, the miR‐211‐5p/Dyrk1A pathway may be critically involved in the pathogenesis of depression and serve as a potential therapeutic target for the treatment of depression." (PMID 34121317, 2021). "Therefore, in CUMS‐exposed rats, this activation of the Dyrk1A/ASK1/JNK/p38 signalling pathway may indicate one of the potential mechanisms through which the activation of neuronal apoptosis within the CA1 region eventually results in depression." (PMID 34121317, 2021). "In addition, the increases in neuronal apoptosis within the CA1 area and depression‐like behaviours induced by CUMS were also prevented by an up‐regulation of miR‐211‐5p, suggesting that the CUMS‐induced miR‐211‐5p deficits may result in depression via elevating Dyrk1A levels." (PMID 34121317, 2021).
gastrointestinal stromal tumor (4 papers, 2020 to 2023). "At least in some tumor types, such as the primary ovarian cancer spheroids and gastrointestinal stromal tumors (GIST), the pro-survival role of DYRK1A is mediated by promoting the DREAM complex formation and entry into G0/G1 arrest." (PMID 37900285, 2023).
osteosarcoma (4 papers, 2008 to 2022). A usually aggressive malignant bone-forming mesenchymal neoplasm, predominantly affecting adolescents and young adults. "As an example of this, we selected for validation one of the KGDs associated with RB1 mutation in osteosarcoma, DYRK1A (p = 6.8 × 10−3), a component of the DREAM complex previously identified as a protein interaction partner of RB1." (PMID 26947069, 2016). "In two independent microarray studies, DYRK1A was among the genes upregulated by overexpression of the transcription factor E2F1 in the human U2OS osteosarcoma cell line and in murine NIH3T3 fibroblasts." (PMID 18366763, 2008). "Individual siRNAs designed to target a gene (as we have shown in the case of DYRK1A dependency in RB1 null cell lines) or small molecule inhibitors (as we have shown for the FGFR sensitivity of osteosarcoma cell lines) might be used as a form of validation." (PMID 26947069, 2016).
autoimmune disease (3 papers, 2023 to 2025). A disorder resulting from loss of function or tissue destruction of an organ or multiple organs, arising from humoral or cellular immune responses of the individual to their own tissue constituents. "Drugs targeting DYRK1A have been developed for cancer treatment, and their inhibitory effects on DYRK1A also contribute to alleviating CSR in autoimmune diseases and allergies." (PMID 39144468, 2024). "Nonetheless, suppression of DYRK1A by these inhibitors might be useful for the attenuation of CSR in autoimmune diseases and allergies." (PMID 36927854, 2023).
Autoimmunity (3 papers, 2021 to 2025). The occurrence of an immune reaction against the organism's own cells or tissues. "Additionally, it has been demonstrated that DYRK1A regulates B cell survival and B cell autoimmunity via activation of NF-κB." (PMID 40148558, 2025). "Importantly, the DYRK1A inhibitor harmine potently attenuated inflammation in multiple experimental murine models of systemic autoimmunity and mucosal inflammation." (PMID 40519271, 2025). "The reports summarized in this article strongly support an IFN-independent role for DYRK1A in inflammation and autoimmunity, which may drive or further potentiate a dysregulated immune microenvironment." (PMID 40519271, 2025). "As one example, DYRK1A inhibition may benefit both autoimmunity and beta cell regeneration in T1D." (PMID 34335466, 2021). "However, conjugating DYRK1A inhibitors to a beta cell-specific targeting molecule may actually be undesirable, depriving them of beneficial effects on autoimmunity and/or adipocytes." (PMID 34335466, 2021).
COVID-19 (3 papers, 2022 to 2023). A disease caused by infection with severe acute respiratory syndrome coronavirus 2. "This drug is a potent inhibitor of DYRK1A in vitro, as well as in Drosophila and mouse models of DYRK1A overexpression and is currently in clinical trials for treating cancer and COVID-19." (PMID 37900285, 2023). "Finally, a role of DYRK1A gene in the resistance against the severe acute respiratory syndrome coronavirus 2 (SARS-CoV-2), the causative agent of coronavirus disease 2019 (COVID-19), has been recently suggested." (PMID 36012629, 2022).
Hypertension (3 papers, 2022 to 2025). The presence of chronic increased pressure in the systemic arterial system. "Niraparib-induced hypertension may be caused by the off-target inhibition of the kinase DYRK1A, which may increase levels of neurotransmitters in the dopaminergic system." (PMID 39796639, 2024). "The unique inhibition of DYRK1A by niraparib could also contribute to the hypertension reported." (PMID 35401230, 2022).
Insulin resistance (3 papers, 2018 to 2022). Increased resistance towards insulin, that is, diminished effectiveness of insulin in reducing blood glucose levels. "Consistent with this, our data demonstrated that DYRK1A ameliorated insulin resistance in both SY5Y and primary neurons by elevating IRS-1 protein." (PMID 31723029, 2019). "It would be interesting to further examine if DYRK1A regulates insulin resistance, particularly in the brain." (PMID 31723029, 2019). "SAHH and Dyrk1A gene expression in the islet correlated negatively with insulin resistance." (PMID 35681432, 2022). "Furthermore, DYRK1A overexpression ameliorated chronic high insulin-induced insulin resistance in SH-SY5Y cells as well as in primary rat neurons." (PMID 31723029, 2019). "However, in cells transfected with DYRK1A, moderate insulin responsiveness was observed with increased levels of Ser-473 AKT phosphorylation (288.5 ± 4.0% of control, p < 0.0001), indicating DYRK1A ameliorate insulin resistance (lane 8 versus 7)." (PMID 31723029, 2019). "Moreover, DYRK1A up-regulation of IRS-1 ameliorates insulin resistance induced by chronic high insulin exposure in SH-SY5Y cells and rat primary neurons." (PMID 31723029, 2019). "Moreover, DYRK1A ameliorated insulin resistance in SH-SY5Y and rat primary neurons." (PMID 31723029, 2019).
ischemic stroke (3 papers, 2018 to 2025). A stroke disorder caused by obstruction of blood flow to the brain, due to thrombotic (local blood clot formation) or embolic (due to a blood clot or other material traveling from another site) event. "Meanwhile, the overexpression of DYRK1A in the brain damage after ischaemic stroke could initiate activity of apoptotic factors or stimulates the pro‐apoptotic pathways ASK1/JNK under oxidative stress." (PMID 34121317, 2021).
osteoarthritis (3 papers, 2020 to 2025). A noninflammatory degenerative joint disease occurring chiefly in older persons, characterized by degeneration of the articular cartilage, hypertrophy of bone at the margins and changes in the synovial membrane. "More recent data has shown that conditional reduction of Dyrk1a in murine chondrocytes results in increased progression of osteoarthritis (OA), suggesting a protective effect of Dyrk1a in disease progression, potentially via modulation of the EGFR-ERK signaling in articular chondrocytes." (PMID 39308945, 2024).
pancreatic adenocarcinoma (3 papers, 2014 to 2021). "report that DYRK1A is widely overexpressed among pancreatic adenocarcinomas, resulting in increased production of oncogenic hepatocyte growth factor, and that inhibition of DYRK1A by harmine attenuates the growth of pancreatic adenocarcinoma cells in vitro and in vivo." (PMID 34335466, 2021).
scoliosis (3 papers, 2018 to 2025). A congenital or acquired spinal deformity characterized by lateral curvature of the spine. "Current early intervention treatments recommended for individuals diagnosed with DYRK1A haploinsufficiency include physical therapy to increase mobility and modulate risk for scoliosis and other musculoskeletal symptoms." (PMID 39308945, 2024).
triple-negative breast carcinoma (3 papers, 2021 to 2024). An invasive breast carcinoma which is negative for expression of estrogen receptor (ER), progesterone receptor (PR), and human epidermal growth factor receptor 2 (HER2). "Altogether, our results define DYRK1A as an important therapeutic target for both colon cancer and triple negative breast cancer and highlight DYRK1A pharmacological inhibition as a potential new therapeutic approach for these cancer patients." (PMID 38839871, 2024). "In this study, we explored the role of DYRK1A in solid tumor models, including colorectal and triple negative breast cancer (TNBC)." (PMID 38839871, 2024). "In this study, we show that DYRK1A acts as a -tumorigenic kinase in two of the most aggressive types of solid tumors, colon cancer and triple negative breast cancer." (PMID 38839871, 2024). "In this study, we investigated the role of DYRK1A kinase in regulating cancer progression and evaluated the therapeutic potential of DYRK1A inhibition in invasive solid tumors, including colon and triple-negative breast cancers." (PMID 38839871, 2024). "Our study, importantly, also highlights a new therapeutic strategy, targeting DYRK1A, with promising results to sensitize the tumors to G1/S phase-specific chemotherapy treatment in both triple negative breast cancer and colon cancer." (PMID 38839871, 2024).
type 1 diabetes (3 papers, 2021 to 2025). "Furthermore, DYRK1A may represent a target for the treatment of diabetes Type 1 and 2, as the kinase is involved in pancreatic β-cell proliferation." (PMID 34832952, 2021).
acute lymphoblastic leukemia (2 papers, 2024 to 2025). Leukemia with an acute onset, characterized by the presence of lymphoblasts in the bone marrow and the peripheral blood. "Unbiased kinome-wide CRISPR screening identified DYRK1A as a potential therapeutic target in KMT2A-rearranged (KMT2A-R) B-acute lymphoblastic leukemia (ALL)." (PMID 40148558, 2025).
Brachycephaly (2 papers, 2023 to 2025). An abnormality of skull shape characterized by a decreased anterior-posterior diameter. "The Tg(Dyrk1a) model, overexpressing Dyrk1a alone, showed strong brachycephaly and reduced premaxilla and nasal bone." (PMID 40982554, 2025). "Thus, Dyrk1a overdosage is essential and sufficient for brachycephaly, but other genes are responsible for the mandibular phenotypes observed in DS." (PMID 40982554, 2025). "Overall, this comparison confirmed the hypothesis and the role of Dyrk1a overdosage in inducing the brachycephaly." (PMID 40982554, 2025). "First, we confirmed the role of Dyrk1a in the neurocranium brachycephaly." (PMID 40982554, 2025). "We hypothesise that increased dosage of Dyrk1a leading to reduced proliferation of NC-derived cells results in smaller facial and frontal bones, and aberrant fusion of the synchondroses, which together lead to brachycephaly and midfacial hypoplasia." (PMID 37102702, 2023).
colon cancer (2 papers, 2024). "For this, we generated DYRK1A gene knockouts (KOs) in HCT-116 colon cancer cells, SUM-159 and MDA-MB-231 TNBC cells." (PMID 38839871, 2024). "Briefly, NT and DYRK1A-KO HCT-116 colon cancer cells were transplanted subcutaneously in male NSG mice." (PMID 38839871, 2024). "As shown in this study, DYRK1A KO leads to inhibition of colony formation in vitro as well as inhibition of tumor formation in vivo in preclinical models of breast and colon cancers." (PMID 38839871, 2024). "This will be critical for selecting proper combinatorial chemotherapy drug treatment when using DYRK1A inhibitors in breast and colon cancer patients." (PMID 38839871, 2024). "Using preclinical models of colon cancer in vivo, we also found that DYRK1A inhibition not only led to restriction of tumor growth but also significantly inhibited the spread of the tumors to distant secondary organs such as the lungs, liver and kidney." (PMID 38839871, 2024). "Finally, we further tested the ability of DYRK1A inhibition to enhance and promote cancer cells response to chemotherapy treatment, in more clinically relevant settings, using an in vivo colon cancer and TNBC xenograft transplantation models." (PMID 38839871, 2024). "To assess whether DYRK1A KO also affect colon cancer progression and metastasis, we used an experimental metastasis preclinical model." (PMID 38839871, 2024). "We found that blocking DYRK1A gene expression or pharmacological inhibition of its kinase activity via harmine efficiently blocked primary tumor formation and the metastatic tumor spread in preclinical models of breast and colon cancers." (PMID 38839871, 2024). "Interestingly, as shown in, blocking DYRK1A gene expression in colon cancer significantly reduced the tumor volume over time as well as the tumor weight at experimental end point." (PMID 38839871, 2024). "Interestingly, we found that DYRK1A KO led to a significant inhibition of cancer cell proliferation, compared to NT-KOs, in both colon cancer and TNBC cells." (PMID 38839871, 2024).
gastric cancer (2 papers, 2019 to 2025). A primary or metastatic malignant neoplasm involving the stomach. "Given the intricate pathogenesis of gastric cancer and the limited efficacy of current metastasis‐targeted interventions, innovative therapeutic strategies—such as circRNA‐based modulation, OGT inhibitors, and DYRK1A kinase‐targeted therapy—are urgently needed." (PMID 41117067, 2025).
Gliosis (2 papers, 2022). Gliosis is the focal proliferation of glial cells in the central nervous system. "Gliosis has been observed in magnetic resonance images of DYRK1A patients younger than 6-years-old16, suggesting that DYRK1A haploinsufficiency may also enhance glial cell production in humans." (PMID 36402907, 2022).
heart failure (2 papers, 2016 to 2024). Inability of the heart to pump blood at an adequate rate to meet tissue metabolic requirements. "Like MAO-A, DYRK1A and 1B may be overexpressed in heart failure and impair hyperplasia and mitochondrial function, respectively." (PMID 39335522, 2024).